TMIGD1 (transmembrane and immunoglobulin domain containing 1)
Description:
May control cell-cell adhesion, cell migration and proliferation, cell morphology, and protects renal epithelial cells from oxidative cell injury to promote cell survival.
Synonyms: TMIGD; UNQ9372
Tractability: Antibody: UniProt places it where antibodies can reach, with high confidence; its Gene Ontology location is reachable by antibodies, with high confidence; UniProt predicts a signal peptide or a membrane-spanning region.
Gene: Protein-coding gene on chromosome 17 (30,315,839 to 30,334,098, reverse strand). Ensembl gene ENSG00000182271.
Subcellular location: Cell membrane; Cytoplasm
Subcellular location (Human Protein Atlas): Cytosol; Mitochondria
Gene Ontology:
Molecular function: protein binding; cell adhesion mediator activity; protein homodimerization activity
Biological process: intestinal epithelial cell migration; negative regulation of apoptotic process; negative regulation of epithelial cell proliferation; regulation of cell migration; regulation of cell population proliferation; regulation of membrane permeability; regulation of protein kinase activity; cell migration; cell-cell adhesion
Cellular component: adherens junction; cytoplasm; plasma membrane; neuron projection; cell surface
Genetic constraint (gnomAD): Loss-of-function variants: 21 observed, 22.61 expected, observed/expected ratio (o/e) 0.93, 90% interval 0.66 to 1.34. The upper end of that interval is the gene's LOEUF score, 1.34, which puts it in group 5 of 6, group 1 being the genes least tolerant of losing a copy. Missense variants: 272 observed, 265.67 expected, observed/expected ratio (o/e) 1.02, 90% interval 0.93 to 1.13. Synonymous variants: 95 observed, 98.02 expected, observed/expected ratio (o/e) 0.97, 90% interval 0.82 to 1.15.
Homologues: Orthologues: chimpanzee TMIGD1 (99% identical), macaque TMIGD1 (93% identical), pig TMIGD1 (78% identical), dog TMIGD1 (77% identical), mouse Tmigd1 (73% identical), rabbit TMIGD1 (73% identical), rat Tmigd1 (72% identical), guinea pig TMIGD1 (70% identical), tropical clawed frog tmigd1 (40% identical), zebrafish tmigd1 (29% identical).
Diseases named in the same sentence as TMIGD1 in open-access papers:
TMIGD1 is named in the same sentence as 23 diseases in open-access papers, as found by Europe PMC text mining. Sharing a sentence is not in itself a finding about the gene and the disease. The quoted sentences say what the papers report.
colon carcinoma (7 papers, 2015 to 2023). "Several unbiased studies describe a strong and highly significant reduction of TMIGD1 gene expression in colon cancer in humans with a progressive downregulation during disease progression." (PMID 37430142, 2023). "TMIGD1, which is a putative tumor suppressor, can induce G2-M cell cycle checkpoint arrest in colon cancer cells and is correlated with poor overall survival." (PMID 36293321, 2022). "Furthermore, our study suggests that loss of TMIGD1 in human cancers, which was previously reported in renal and colon cancers, could result in the activation of pro-tumorigenic signaling cascades, including the activation of ERM proteins that contribute to tumor progression." (PMID 34503512, 2021). "Our previous analysis of data sets from The Cancer Genome Atlas and our own immunohistochemical analysis revealed that low expression of TMIGD1 correlates with poor survival in renal and colon cancers." (PMID 34503512, 2021). "Re-expression of TMIGD1 in renal and colon cancer cell lines inhibits cell proliferation and induces G2/M cell cycle checkpoint arrest." (PMID 34503512, 2021). "A RNAseq-based comparison of hyperplastic polyp lesions with colorectal adenoma lesions identified TMIGD1 among the top 10 down-regulated genes in colorectal adenoma, confirming a gradual downregulation of TMIGD1 expression during the development of colon cancer." (PMID 37087524, 2023). "We thus compared with the same gene expressions (up-regulated transcripts: SLC16A4, DSC3, ALDOB, EPHX4, ARHGAP24; and down-regulated transcripts (MS4A12, TMIGD1, CASP5) in 5 colon cancer lines: HCT 116, Caco2, HT-29, Lovo, and C32." (PMID 25929336, 2015). "Additional observations describing reduced TMIGD1 expression in CRC samples were made in studies comparing colonic non-adenomatous, non-neoplastic tissue with colonic tumor tissue, with TMIGD1 being among the 11 most significantly downregulated genes in colonic tumor tisse." (PMID 37087524, 2023). "In addition, the expression of Tmigd1 (transmembrane and immunoglobulin domain containing 1) is sequentially reduced in normal-nonpolypoid-polypoid-cancer and in colon cancer cell lines, indicating that Tmigd1 might be involved in intestinal cell differentiation." (PMID 28170448, 2017).
colorectal cancer (5 papers, 2018 to 2023). A primary or metastatic malignant neoplasm that affects the colon or rectum. "Similar to human colorectal cancers, MALAT1 is slightly downregulated in the murine colonic polyps compared to healthy tissues, a pattern also observed in genes encoding known colorectal cancer tumor suppressor molecules, such as Mbd1 and Tmigd1." (PMID 37325561, 2023). "Since inflammation is a known risk factor for colorectal cancer it is conceivable that an inflammation-induced downregulation of TMIGD1 is a causative factor contributing to the development of colorectal cancer." (PMID 37087524, 2023). "Together with the observation of TMIGD1 downregulation in colorectal cancer, they also suggest that TGFβ-triggered downregulation of TMIGD1 via HNF4α is part of the TGFβ-induced EMT programme." (PMID 37087524, 2023). "Additional observations based on microarray analyses and on bioinformatic analyses of published datasets further confirmed a downregulation of TMIGD1 expression in human colorectal cancer." (PMID 37087524, 2023). "The findings herein identify TMIGD1 as a novel tumor suppressor gene and provide new insights into the pathogenesis of colorectal cancer and a novel potential therapeutic target." (PMID 35093172, 2022). "In an additional strategy to probe the effect of TMIGD1 in filopodia protrusions, we expressed TMIGD1 in a colorectal carcinoma cell line, RKO cells and examined filopodia structures via phalloidin staining." (PMID 34503512, 2021). "In agreement with our view of TMIGD1 as a candidate tumor suppressor gene, a recent study demonstrated that TMIGD1 expression was also downregulated in human pre-invasive colorectal cancer." (PMID 29515762, 2018). "Mice with a constitutive inactivation of the Tmigd1 gene have an altered intestinal tissue morphology and develop intestinal adenoma, strongly suggesting that low TMIGD1 levels are not just correlative but rather causative for colorectal cancer development." (PMID 37087524, 2023). "TMIGD1 is a cell adhesion receptor that has drawn attention after the discovery that its expression is progressively downregulated during the development of colorectal cancer in humans." (PMID 37087524, 2023). "Meanwhile, a number of studies have confirmed a highly significant downregulation not only in colorectal cancer but also in renal cancer, strongly supporting a tumor-suppressive function of TMIGD1 and suggesting that TMIGD1 expression may be used as a prognostic marker." (PMID 37087524, 2023). "Similar findings were obtained in colorectal cancer cells, suggesting that the activation of the p38α MAPK pathway is a major molecular mechanism through which TMIGD1 suppresses cellular transformation." (PMID 37087524, 2023). "Among several thousand genes that were analyzed the Tmigd1 gene stood out as its mRNA level was progressively downregulated from normal tissue to non-polypoid lesions to polypoid lesions to colorectal cancer tissues." (PMID 37087524, 2023). "The first study that identified TMIGD1 as a putative tumor suppressor is based on a systematic comparative transcriptome analysis of normal colonic tissue, precancerous non-polypoid lesions, pre-cancerous polypoid lesions, and colorectal cancer (CRC) lesions." (PMID 37087524, 2023).
Crohn disease (4 papers, 2023 to 2025). A gastrointestinal disorder characterized by chronic inflammation involving all layers of the intestinal wall, noncaseating granulomas affecting the intestinal wall and regional lymph nodes, and transmural fibrosis. "Also, several studies found a significant downregulation of TMIGD1 gene expression in diseases associated with chronic intestinal inflammation such as Crohn’s disease or inflammatory bowel disease, conditions which promote carcinogenesis." (PMID 37430142, 2023). "A recent study 19 found that knocking out Transmembrane and immunoglobulin domain-containing protein 1 (TMIGD1) impairs intestinal barrier integrity in Crohn's disease." (PMID 40384864, 2025). "Importantly, CAMs such as Transmembrane and immunoglobulin domain-containing protein 1 (TMIGD1) and E-Cad have been suggested to be directly participated in Crohn’s disease and gastrointestinal tumorigenesis, respectively." (PMID 40825946, 2025).
renal carcinoma (4 papers, 2018 to 2023). A carcinoma arising from the epithelium of the renal parenchyma or the renal pelvis. "Similar to the expression levels of TMIGD1, the levels of C/EBPβ are low in renal cancer as well as in kidney cancer-derived cell lines." (PMID 37087524, 2023). "Here, we review the molecular characteristics of TMIGD1, its interaction with cytoplasmic scaffolding proteins, the regulation of its expression, and its downregulation in colorectal and renal cancers." (PMID 37087524, 2023). "The result showed that expression of C/EBPβ in renal cancer is significantly reduced and its reduced expression closely correlated with the expression of TMIGD1 (5 out 5 cases)." (PMID 29515762, 2018). "To gain insight into possible function of TMIGD1 in renal cancer, we decided to examine TMIGD1 status in the publically available RCC database." (PMID 29515762, 2018). "Importantly, ectopic expression of TMIGD1 in a renal cancer cell line limits tumor formation in vivo after adoptive transfer into nude mice." (PMID 37087524, 2023). "For example, the expression status of TMIGD1 in human cancers, such as colon and renal cancers, could determine whether moesin and ezrin function as pro- or anti-tumorigenic factors." (PMID 34503512, 2021). "Next, we examined a cohort of 24 human renal cancer biopsy samples for expression of TMIGD1." (PMID 29515762, 2018). "Here, we present evidence that TMIGD1 binds to ERM family proteins (moesin and ezrin), regulates the stability of microtubules and modulates cell migration in renal cancer cells, implicating TMIGD1 as a potential cancer therapeutic target." (PMID 34503512, 2021). "To identify TMIGD1 interacting proteins in renal cancer cells, we generated a recombinant GST-fusion protein encompassing the cytoplasmic domain of human TMIGD1." (PMID 34503512, 2021). "In this study, we demonstrate that transmembrane and immunoglobulin domain-containing 1 (TMIGD1) is a novel tumor suppressor that is highly expressed in normal renal tubular epithelial cells, but it is downregulated in human renal cancer." (PMID 29515762, 2018).
colitis (3 papers, 2023 to 2025). Inflammation of the colon. "TMIGD1 expression was markedly decreased in inflamed colonic mucosa of patients with CD and in mouse colitis." (PMID 37542259, 2023). "Macrophage-derived exosomal miR-223 plays a novel role in the development of dextran sulfate sodium salt (DSS)-induced colitis by inducing intestinal barrier dysfunction via the inhibition of transmembrane and immunoglobulin domain-containing protein 1 (TMIGD1)." (PMID 40659888, 2025). "TMIGD1 was downregulated in inflamed intestinal mucosa of patients with CD and mice colitis models." (PMID 37542259, 2023). "After restoring TMIGD1 and BANF1, both WT and Tmigd1INT-KO mice with colitis exhibited increased body weight and colon length, less bloody diarrhea, and lower disease activity." (PMID 37542259, 2023). "We intraperitoneally injected adenovirus (ADV) to boost TMIGD1 and BANF1 expression in mice 2 days before inducing colitis with DSS." (PMID 37542259, 2023). "Downregulation of both Tmigd1 mRNA (0.335-fold, p<0.001 in DSS-induced colitis; 0.245-fold, p<0.001 in TNBS-induced colitis) and protein levels in murine colonic epithelia were detected." (PMID 37542259, 2023). "We have not observed spontaneous colitis in CDHR5‐deficient mice nor has it been reported in CDHR2‐ and TMIGD1‐deficient mice." (PMID 37691494, 2023).
kidney cancer (2 papers, 2021 to 2023). Primary or metastatic malignant neoplasm involving the kidney. "Our analysis demonstrated that TMIGD1 mRNA is downregulated in all the major kidney cancer types including, kidney clear cell renal cell carcinoma (KIRC), kidney papillary renal cell carcinoma (KIRP) and chromophobe renal cell carcinoma (KICH)." (PMID 34503512, 2021). "Importantly, ectopic expression of C/EBPβ in a kidney cancer-derived cell line results in a strong upregulation of TMIGD1 expression." (PMID 37087524, 2023). "The median expression of TMIGD1 mRNA in pan kidney cancers (KIPAN) was 1.91 versus 3.42 normal." (PMID 34503512, 2021).
renal cell carcinoma (2 papers, 2021 to 2023). "Considering the association of TMIGD1 with moesin, we decided to investigate whether TMIGD1 expression in renal cell carcinoma, 786-0 cell line could modulate microtubule stability." (PMID 34503512, 2021). "Having established a functional link between TMIGD1 and moesin, we asked whether expression profiles of the TMIGD1 and ERM family proteins, moesin and ezrin, correlate with survival of renal cell carcinoma (RCC) patients." (PMID 34503512, 2021).
colonic diseases (1 paper, 2017). "Several downregulated genes including Mal, Prkg2, Amn, Tmigd1, 9030624O13Rik, and Akr1b7 are known to be associated with colonic diseases." (PMID 28170448, 2017).
cyst (1 paper, 2023). A sac-like closed membranous structure that may be empty or contain fluid or amorphous material. "We show that TMIGD1 can recruit Scrib to the lateral membrane domain and that expression of a dominant-negative TMIGD1 mutant disturbs three-dimensional cyst morphogenesis." (PMID 37430142, 2023).
Hypertension (1 paper, 2020). The presence of chronic increased pressure in the systemic arterial system. "In vivo, TMIGD1 expression undergoes a biphasic up- and downregulation in two kidney disease models characterized or favoured by excessive ROS generation, i.e. ischemia/reperfusion-induced oxidative stress and experimentally induced hypertension." (PMID 32303178, 2020).
nephrosclerosis (1 paper, 2018). Hardening of the kidney due to infiltration by fibrous connective tissue (fibrosis), usually caused by renovascular diseases or chronic hypertension. "Expression of TMIGD1 was unchanged in the non-cancerous renal disease, nephrosclerosis (3 cases), compared to the normal/non-diseased kidney tissues (data not shown)." (PMID 29515762, 2018).
renal tumor (1 paper, 2018). "Hence, the data also suggests that downregulation of TMIGD1 in renal tumor cells is associated with increased tumor growth and invasion." (PMID 29515762, 2018). "We posited that downregulation of TMIGD1 in renal tumor could be associated with the altered expression of C/EBPβ." (PMID 29515762, 2018). "We have demonstrated the mechanism by which expression of TMIGD1 in renal tumors is regulated by transcriptional activity of C/EBPβ." (PMID 29515762, 2018). "Our analysis showed that TMIGD1 mRNA was considerably lower in renal tumor cell lines including, 786-0, A498, 769P and TK10 compared to normal kidney mRNA." (PMID 29515762, 2018). "Re-introduction of TMIGD1 into renal tumor cells significantly inhibited tumor growth and metastatic behaviors such as morphogenic branching and cell migration." (PMID 29515762, 2018). "More importantly, the data presented in this present work suggests that reduced expression of TMIGD1 by renal tumor cells provide a significant gain for their tumorigenic properties." (PMID 29515762, 2018). "The data suggests that reduced expression of C/EBPβ could in part explain the downregulation of TMIGD1 in renal tumors." (PMID 29515762, 2018). "Restoring TMIGD1 expression in renal tumor cells stimulated phosphorylation of p38MAK, induced expression of p21CIP1 (cyclin-dependent kinase inhibitor 1), and p27KIP1 (cyclin-dependent kinase inhibitor 1B) expression, key cell cycle inhibitor proteins involved in regulation of the cell cycle." (PMID 29515762, 2018). "Therefore, we re-introduced TMIGD1 into a renal tumor cell line, 786-0 cells via a retroviral system and assessed its function in proliferation of 786-0 cells." (PMID 29515762, 2018). "Considering the stark downregulation of TMIGD1 in human RCC tumors, we hypothesized that downregulation of TMIGD1 in renal tumors could play an important role in the biology of renal tumor cells." (PMID 29515762, 2018).
cancer (8 papers, 2014 to 2023). A tumor composed of atypical neoplastic, often pleomorphic cells that invade other tissues. "It will thus be important to study a cause-and-effect relationship between loss of TMIGD1 expression and Scrib mislocalization during cancer development." (PMID 37430142, 2023). "Emerging evidence on the role of TMIGD1 in human cancers points to TMIGD1 as a novel tumor suppressor." (PMID 34503512, 2021). "We show for the first time that TMIGD1 binds to ERM family proteins, regulates the stability of microtubules and modulates cell migration, implicating TMIGD1 as an attractive potential cancer therapeutic target." (PMID 34503512, 2021). "To address this question, we analyzed 786-0 cells expressing TMIGD1 for activation of twenty major cancer pathways consisting of 70 individual proteins via a recently developed immuno-paired-antibody detection system (ActiveSignal Assay) analysis platform." (PMID 29515762, 2018). "TMIGD1 and HHLA2 were previously reported to be potential therapeutic targets in cancers." (PMID 35506368, 2022).